DES (desmin)
Diseases named in the same sentence as DES in open-access papers (continued):
Sharing a sentence is not in itself a finding about the gene and the disease.
tumor (continued). "The tumor cells expressed CD99, synaptophysin, CD56, MUC4, and EMA (focal), but not AE1/AE3, S100, smooth muscle actin, desmin, CD34, chromogranin A, GFAP, NKX2-2, PAX7, and INSM1." (PMID 39249507, 2024). "Tumor cells were positive to vimentin and CD99, but negative to S-100, SMA, HHF-35, desmin, CD31, CD34, STAT-6 and pan-cytokeratin (AE1/AE3)." (PMID 39462411, 2024). "Immunohistochemical staining revealed that the tumor was positive for alpha-smooth muscle actin, but negative for CD34, desmin, keratin 18, S-100 protein, melan A, c-kit, and STAT6." (PMID 38805072, 2024). "Immunohistochemical results showed that tumor cells diffusely express CD34, p75, and partially express EMA (cytoplasm), while S-100, Desmin, AE1/AE3, actins, FXIIIa all tested negative." (PMID 38388419, 2024). "Immunohistochemically, the tumor was positive for alpha-smooth muscle actin, but negative for CD34, desmin, keratin 18, S-100 protein, melan A, c-kit, and STAT6." (PMID 38805072, 2024). "On IHC, atypical spindle cell/ pleomorphic lipomatous tumor shows variable positivity for CD34, S100 protein, and desmin, while MDM2 and CDK4 are often negative." (PMID 38916002, 2024). "During the first round of immunohistochemical stains, the tumor cells showed positivity for CD56, CD99 (diffuse to patchy), INSM1, and NKX2.2, while they were negative for desmin, cytokeratin, SS18-SSX, and WT-1." (PMID 36765856, 2023). "In each of the lesions, immunochemistry staining was positive for nuclear β-catenin in about 30% of the tumor, while it was negative for CD117, DOG1, S100, SM Actin, Desmin and CD34; proliferation index Ki 67 was < 5%." (PMID 35913675, 2023). "SMA, desmin and CD123 are not lineage specific and the morphology and phenotype did not support a tumour with smooth muscle differentiation or a BPDCT." (PMID 36344905, 2023). "Normally, BSNS tumours show immunoreactivity for S100, SMA and sometimes desmin but demonstrate no reaction with CD34, STAT6, EMA and myogenin, which was also included in the report of all three cases presented." (PMID 38027532, 2023). "The post-operative pathologicalimmunohistology showed the tumor to be a Ki-67 < 1%, SDHB+, SMA+, CD34+, CD117+, DOG-1+,and Desmin+ GIST with tumor regression grade 2 and negative margins." (PMID 36632625, 2023). "IHC studies demonstrated that the tumor cells were patchily positive for CD117, Melan-A and desmin, but negative for DOG1." (PMID 37041531, 2023). "Immunohistochemically (IHC), tumor cells were positive for SMA, MDM2, and p16; the cells were negative for desmin, MyoD1, Myogenin, pan-cytokeratin, S100, SOX10, HMB45, Malen-A, CD34, CD31, CD99, and ALK." (PMID 37735390, 2023). "The tumor cells were negative for AE1/3, Cam5.2, CKIT, DOG1, CD99, SOX10, S100, HMB45, MelanA, Syn, CgA, Trypsin, Desmin, SMA, Caldesmon, collagen type 4, Laminin, Inhibin, Calretinin, STAT6, CD34, ERG, WT1, ER, PR, and SALL4." (PMID 36928336, 2023). "Immunohistochemically, the tumor cells were positive for smooth muscle actin (SMA) and negative for cytokeratin, desmin, H-Caldesmon, CD34, S100, ALK, and β-catenin." (PMID 36741963, 2023). "Immunohistochemically, the tumour cells were diffusely positive for smooth muscle actin and GRM1, and negative for S100 protein, desmin and cytokeratin AE1AE3." (PMID 36810795, 2023). "The tumour cells express SMA and vimentin; partially express desmin, CD34, CD68 and ALK; and do not express CK or S100." (PMID 36855132, 2023). "The tumor cells expressed SATB2, Bcl-2, TLE1, SMARCB1, but not CK, EMA, CD34, SMA, Desmin, S-100, CD99, STAT6, MyoD1, Myogenin, and Ki-67 LI is about 10%." (PMID 37361584, 2023). "The SMA, desmin, CD117, and CK7 reactions were negative; hence, the tumor was interpreted as a spindle cell variety (sub-type) of clear RCC." (PMID 37927619, 2023). "Tumour cells in CMN are positive for vimentin, desmin and actin but negative for CD34 and epithelial markers, however diagnosis is primarily based on morphology." (PMID 37203959, 2023).
tumor (continued). "Immunostaining of the tumor cells showed positive staining for KIT and DOG1 and negative staining for S100 and desmin." (PMID 37789344, 2023). "Immunohistochemical stains were helpful (the tumor cells were positive for S100, while negative for SMA, desmin, ER, and PR) to exclude the possibility of mucinous cystic neoplasm." (PMID 35001360, 2022). "In this case, the IHC staining results suggested that the patient’s tumor was diffusely positive for CD117, vimentin, CD56 and NSE and focally positive for desmin, negative for other markers, and had a ki-67 level of ~ 40%." (PMID 35488288, 2022). "Immunochemical analysis revealed positive tumor staining for c-kit protein and alpha-smooth muscle actin and negative staining for CD34, desmin, and S-100 protein." (PMID 36214924, 2022). "Mural nodules: polygon or spindle and giant tumor cells showed strong positive expression of cytokeratin (CK), epithelial membrane antigen (EMA), and vimentin (VIM), while CD163, S-100, Desmin, CD31, and MyoD1 were negative." (PMID 35836292, 2022). "Tumor cells were positive for pan-cytokeratin (Pan CK), synaptophysin, vimentin, and S100 (focal) and negative for CD45, CD99, and desmin." (PMID 36259025, 2022). "The tumor was positive for CD117, Vim, CD56 and NSE and showed focal expression of desmin but was negative for myogenin, S-100, SYN, INSM1, CD34, STAT6, INI-1, Brachyury, ERG, TLE1, AE1/AE3, WT-1, CD99 and SMA." (PMID 35488288, 2022). "Mitotic activity was low, and the tumor showed diffuse expression of α-SMA, desmin, caldesmon, and calponin, without expression of myogenin, MyoD1, CD34, EMA or PS100." (PMID 36421692, 2022). "The tumor did not reveal any specific differentiation (immunohistochemical stains showed that the tumor cells were negative for pancytokeratin, SMA, desmin, CD117, DOG1, CD34S100, Melan-A, and HMB45)." (PMID 35001360, 2022). "There was a lot of collagen matrix around the tumor cells, and the immunohistochemical markers of the tumor cells were positive for actin and vimentin but negative for SMA, desmin, and S-100." (PMID 36337871, 2022). "Immunohistochemically, the tumor cells were positive for CD117, vimentin, CD56 and NSE and focally expressed desmin; the cells were negative for myogenin, S-100, SYN, INSM1, CD34, STAT6, INI-1, Brachyury, ERG, TLE1, AE1/AE3, WT-1, CD99 and SMA." (PMID 35488288, 2022). "Immunohistochemically, the tumor cells of case No. 1 were positive for AE1/AE3, calretinin, D2-40, focal positive for HBME-1 and negative for HMB45, Melan-A, Desmin, Actin, and S100." (PMID 34248850, 2021). "Immunohistochemistry, the tumor cells were diffusely positive for S-100 protein, SOX-10 and CD68, while they were completely negative for desmin, DOG-1, AE1/AE3 and P63." (PMID 34243786, 2021). "Tumor cells showed negative staining for the following markers: CD117 (n = 4), CD34 (n = 3), DOG-1 (n = 4), STAT6 (n = 2), EMA (n = 2), Desmin (n = 3), and SMA (n = 3)." (PMID 33588954, 2021). "The tumor was negative for AE1-AE3 cytokeratin, epithelial membrane antigen (EMA), S100 protein, smooth muscle actin (SMA), and desmin." (PMID 34211794, 2021). "IHC studies show the tumor cells to be positive for FLI-1 and negative for S100 protein, SOX10, desmin, myogenin, WT1, SMA, CD34 and pan-cytokeratin." (PMID 34745213, 2021). "The tumor cells were diffusely positive for S-100 protein, SOX-10 and CD68, while they were completely negative for desmin, DOG-1, AE1/AE3 and P63." (PMID 34243786, 2021).
tumor (continued). "The consistent immunohistochemical staining results with the primary tumor of the colon were positive for HMB-45, caldesmon, and S100 and negative for desmin and α-smooth muscle actin." (PMID 34716849, 2021). "In our case, we found that the tumor specimen was positive for CK, CK7, P63, and vimentin, but negative for EMA, TTF-1, smooth muscle actin, desmin, carletinin, and D2-40." (PMID 34766593, 2021). "The tumor cells were positive for Trk and SMA, but negative for S100, CD34, ALK, CD10, desmin, myogenin, CD99, CD56, CK, EMA, and STAT6." (PMID 32957984, 2020). "The tumor cells were robustly and diffusely positive for Trk, S100-protein, CD34, and nestin, but negative for CD56, SMA, desmin, myogenin, STAT6, EMA, CK, CD1a, CD21, CD35, CD43, WT-1(c-terminal), MelanA, HMB45, BRAF, and ALK." (PMID 32957984, 2020). "Immunohistochemical staining is required for the diagnosis of SFTP; the tumor cells are positive for STAT6, CD34, CD99, and BCL2, whereas they are negative for desmin, S-100, and alpha-SMA." (PMID 32638177, 2020). "Immunochemical studies showed that the tumor was positive for SMA and collagen type IV, and negative for C-Kit, CD34, desmin, and S100." (PMID 33270165, 2020). "The tumor was negative for S100 protein, cytokeratin (CK), glial fibrillary acidic protein (GFAP), CK7, SOX10, CD31, CD34, desmin, MyoD1, myogenin, smooth muscle actin (SMA), CD117, β-catenin and MUC4." (PMID 31915021, 2020). "Immunohistochemically, the tumor cells lacked of reactivity with CD34; CK5/6, EMA, SOX10, S100, desmin, SMA, MDM2 and GFAP." (PMID 32164724, 2020). "The stellate tumor cells in IMT are immunophenotypically positive for SMA, desmin and ALK, which are negative in PPMS." (PMID 32039736, 2020). "Immunohistochemistry study revealed that the tumor cells were positive for CD4 and CD30, and were negative for cytokeratin, CD3, CD20, CD68, CD163, lysozyme, ALK, S-100, and desmin." (PMID 32547956, 2020). "The tumor cell immunophenotype was positive for vimentin, EMA and negative for CK-pan, TTF-1, CAM5.2, S-100, calponin, SMA, desmin, ALK, CD31 and CD34." (PMID 32039736, 2020). "The tumor cells were negative for any other melanocytic markers such as S100, Melan A, MITF, SOX10, all myogenic markers (SMA, MSA, desmin, caldesmon) and cytokeratins." (PMID 31309284, 2020). "Tumor cells were immunohistologically positive for α-SMA and h-caldesmon; partially positive for desmin; negative for c-kit, CD34, DOG-1, and the S-100 protein; and showed a Ki-67 labeling index of 70–80%." (PMID 33006746, 2020). "The tumor cells were negative for CD117, DOG1, SMA, desmin, S-100, synaptophysin, and chromogranin A. On the basis of the histology and immunostaining profile, the tumor was diagnosed as a malignant SFT of the pancreas." (PMID 33188464, 2020). "Immunohistochemical analysis showed that the tumour was positive for vimentin, CD99, Bcl-2 and CD34 and negative for D2–40, desmin, S-100, SMA and CK and the Ki-67 index was as low as 1%." (PMID 31391089, 2019). "In all of our MFB cases, the tumor cells were immunoreactive for CD34, desmin, SMA, and ER and negative for cytokeratin, p63, CD68, and beta-catenin." (PMID 30989009, 2019). "Immunohistochemical staining showed that the tumor was negative for CD34, c-kit, and S-100 and positive for desmin and α-smooth muscle actin." (PMID 31781464, 2019). "Tumorous cells were negative for AE1/AE3 (Dako), actin (1A4, Dako), desmin (D33, Dako) and CD34 (Qbend-10, Dako) but 80% of tumour cells were positive for epithelial membrane antigen (E29, Dako)." (PMID 31350293, 2019). "Immunohistochemical analysis showed that the tumor cells were positive for S-100 and negative for CD117, DOG-1, desmin, and SMA." (PMID 31049058, 2019). "Based on immunohistochemical examination, the tumour cells were positive for CD34, Bcl2, vimentin, and CD99 and negative for desmin and S-100." (PMID 31391089, 2019).
tumor (continued). "Immunostaining revealed that the tumor cells were positive for TLE1 and BCOR, and negative for cytokeratin (AE1/AE3), Desmin, CD45, S100, CD31, HMB45, and SATB2." (PMID 31702654, 2019). "Immunohistochemical analysis showed that the tumor cells were positive for S-100 and negative for CD117, DOG-1, desmin, and smooth muscle actin." (PMID 31049058, 2019). "The tumor cells were positive for S-100 and negative for CD117, DOG1, CD34, Desmin, smooth muscle actin (SMA) and H-caldesmon (data not shown); the Ki-67 labeling index of the cancer cells was less than 5% (data not shown)." (PMID 31647020, 2019). "Further, immunostaining of tumor cells was positive for TLE1 and BCOR, and negative for cytokeratin (AE1/AE3), Desmin, CD45, S100, CD31, HMB45, and SATB2." (PMID 31702654, 2019). "The tumour cells were positive to vimentin and CD68, and negative to desmin, SMA, S100 protein, EMA, cytokeratins AE1/AE3, CD117, and CD34 antibodies." (PMID 31773099, 2019). "Immunohistochemical analysis showed the tumour cells were positive for ER, PgR, CD34,Desmin, CD99, BCL-2 and negative for H-caldesmon, SMA, c-Kit, S100 protein, MNF116,HMB45 and melan A. Less than 2% of cells were positive for Ki67." (PMID 31131129, 2019). "The tumor is negative for EMA, cytokeratin 7, cytokeratin 20, chromogranin A, synaptophysin, S-100 protein, HMB-45, desmin, SMA, EBV, CD117, DOG1, CD23, CD21, clusterin, MDM2, CD34, D240, and ERG." (PMID 31623602, 2019). "The pathological findings were compatible with GIST and the tumor consisted of spindle cells with positive staining for KIT, CD34, and DOG1 and negative or weak staining for desmin and S-100 protein." (PMID 30943904, 2019). "The tumor cells were positive for DOG1, sporadically positive for CD34 (data not shown) and CD117, and negative for S-100, Desmin, SMA, H-caldesmon, and CK-pan (data not shown)." (PMID 31647020, 2019). "All specimens demonstrated strong positive immunostaining for S-100 and GFAP proteins, whereas the tumor cells were not immunoreactive to DOG1, c-Kit (CD117), CD34, SMA and desmin." (PMID 30045739, 2018). "In our case, tumor cells expressed cytokeratin 5/6 and cytokeratin 7, SMA, S-100 protein, and p63, but they were negative for desmin." (PMID 29489937, 2018). "Like the tumours in SCID/beige mice, these tumours also showed variable staining for VIMENTIN, DESMIN and SMA as well as an absence of staining for MYOD1 and MYOGENIN." (PMID 29731980, 2018). "Tumor cells displayed positivity for cytokeratins 5/6 and 7, smooth muscle antigen (SMA), S100 and p63 proteins, and were negative for desmin, thus indicating the myoepithelial origin." (PMID 29489937, 2018). "The tumor cells showed generally positive for vimentin and negative for h-CALD, CD34, desmin, CD163, AE1/AE3, CK7 and CK20." (PMID 28320435, 2017). "Immunohistochemically, the tumor cells were positive for CD34, bcl-2 and STAT6, whereas alpha-SMA, desmin, and S-100 were negative." (PMID 28063145, 2017). "The tumor cells were negative for CD21, CD23, CD35 and CD1a, CKpan, cam5.2, EMA, HMB45, Melan A, CD3, CD20, Desmin, SMA, and so on." (PMID 28386111, 2017). "Per report, the tumor exhibited weak and focal positivity for CD117 (KIT), vimentin and calretinen, and was negative for SMA, S100, CD34, and desmin." (PMID 28768491, 2017). "In this case, the immunohistochemical findings were compatible with SFT, as the tumor cells were positive for CD34 and bcl-2, whereas alpha-SMA, desmin, and S-100 were negative." (PMID 28063145, 2017). "Immunohistochemistry revealed that tumor cells were positive for HMB45 and SMA, but negative for PAN-CK, desmin, S-100, melan-A, EMA, c-kit, and CD10." (PMID 28270196, 2017). "Immunohistochemically, the tumor cells were positive for AE1/AE3, synaptophysin, desmin, and myogenin but negative for CAM5.2, chromogranin A, S-100 protein, c-kit, and DOG1." (PMID 27250580, 2016).
tumor (continued). "The tumor was strongly immuno-reactive for GFAP, SMARCB/INI-1 was preserved, and the tumor was negative for chromogranin, synaptophysin, Cam 5.2, EMA, desmin, myogenin, neurofilament and mutant-specific IDH1 (R132H)." (PMID 27582545, 2016). "Tumor cells are CD34, CD99, and bcl2 positive, while the S-100 protein, actin, and desmin are negative." (PMID 27579199, 2016). "By contrast, the tumor cells from the primary lesion in case 2 presented with negative staining for α-SMA and positive staining for desmin, while the cells of the recurrent lesion were α-SMA-positive and desmin-negative." (PMID 25624890, 2015). "Immunohistochemically, the tumor cells were positive for vimentin and cluster of differentiation 34, while they were negative for keratin, PDGFRA, smooth muscle actin, desmin, S-100 protein, DOG-1 and c-kit." (PMID 25435986, 2015). "The tumor cells from case 1 demonstrated positive staining for α-SMA protein and negative staining for desmin." (PMID 25624890, 2015). "Immunohistochemical tests showed the tumour only had patchy positivity for AE1/AE3 and negative for the following markers: SMA, Desmin, CD34, S100, EMA, and CD99." (PMID 25888133, 2015). "Immunohistochemically, the tumor cells were positive for cytokeratin (CK) and vimentin, but negative for CK20, CK7, desmin and smooth muscle actin." (PMID 25788994, 2015). "His immunohistochemistry analysis showed that the tumor cells were positive for vimentin, CD34, BCL-2 and beta-catenin, and negative for pan Cytokeratin, p63, Calretinin, SMA, desmin, S100, CD-31, CD-117, DOG1, EMA, STAT6, GRIA2 and WT-1." (PMID 25884588, 2015). "Tumor cells are negative for CK, WT1 and desmin, and the stroma is rich in nerve fiber network, with ganglion cell differentiation commonly observed." (PMID 25037705, 2014). "Immunohistochemical studies revealed that the tumor cells was positive for VIM and MDM2, and was negative for CK, MSA, SMA, DES, S-100 and CD34." (PMID 24444015, 2014). "In the present case, the tumor cells were positive for vimentin, CD68 and Ki-67, and negative for S-100, SMA, desmin, CD31, CD34, ALK and AE1/AE3." (PMID 24959221, 2014). "Normally, the tumor cells are positive for MIC-2 (CD99) and vimentin, and negative for desmin and CK, but are not specific markers for pPNET." (PMID 25013495, 2014). "The tumor cells were immunoreactive for CD10+, PR, and smooth muscle actin (SMA), but negative for desmin, S100, CD34, CD117, cytokeratins AE1AE3, CD68R, and ER." (PMID 24744931, 2014). "In the present case, tumor cells were positive for SMA staining, but no immunoreactivity was observed for CD34, desmin or S-100." (PMID 24396463, 2014). "Muscle-specific actin (MSA), smooth muscle actin (SMA) and desmin (DES) were negative in the tumor cells, eliminating the possibility of a muscle-derived tumor." (PMID 24444015, 2014). "On immunohistochemical staining, the tumor cells were positive for vimentin and CD99, but negative for alpha smooth muscle actin, desmin, and S-100 protein." (PMID 24969223, 2014). "Immunohistochemically, the tumor was positive for CD99, vimentin, neuron specific enolase and chromogranin A, and negative for cytokeratins, CD3, desmin, and leukocyte common antigen." (PMID 23537038, 2013). "The tumor cells were positive for CD117 and CD34, but negative for α-SMA, desmin and S-100 by immunohistochemistry." (PMID 23902675, 2013). "Immunohistochemical (IHC) analysis of the patient’s tumour revealed only focal SMA positivity, whereas tests for Desmin, Caldesmon, S100, CD34, EMA, and Pan-CK were negative." (PMID 24289252, 2013). "By immunohistochemical staining, the tumour cells were positive for CD34, Bcl-2, and SMA and negative for desmin, S100, C-kit, and HMB-45." (PMID 24490095, 2013).